PLA2G2A (phospholipase A2 group IIA)
Description:
Secretory calcium-dependent phospholipase A2 that primarily targets extracellular phospholipids with implications in host antimicrobial defense, inflammatory response and tissue regeneration. Hydrolyzes the ester bond of the fatty acyl group attached at sn-2 position of phospholipids (phospholipase A2 activity) with preference for phosphatidylethanolamines and phosphatidylglycerols over phosphatidylcholines. Contributes to lipid remodeling of cellular membranes and generation of lipid mediators involved in pathogen clearance. Displays bactericidal activity against Gram-positive bacteria by directly hydrolyzing phospholipids of the bacterial membrane. Upon sterile inflammation, targets membrane phospholipids of extracellular mitochondria released from activated platelets, generating free unsaturated fatty acids such as arachidonate that is used by neighboring leukocytes to synthesize inflammatory eicosanoids such as leukotrienes. Simultaneously, by compromising mitochondrial membrane integrity, promotes the release in circulation of potent damage-associated molecular pattern molecules that activate the innate immune response. Plays a stem cell regulator role in the intestinal crypt. Within intracellular compartment mediates Paneth cell differentiation and its stem cell supporting functions by inhibiting Wnt signaling pathway in intestinal stem cell (ICS). Secreted in the intestinal lumen upon inflammation, acts in an autocrine way and promotes prostaglandin E2 synthesis that stimulates Wnt signaling pathway in ICS cells and tissue regeneration (By similarity). May play a role in the biosynthesis of N-acyl ethanolamines that regulate energy metabolism and inflammation. Hydrolyzes N-acyl phosphatidylethanolamines to N-acyl lysophosphatidylethanolamines, which are further cleaved by a lysophospholipase D to release N-acyl ethanolamines. Independent of its catalytic activity, acts as a ligand for integrins. Binds to and activates integrins ITGAV:ITGB3, ITGA4:ITGB1 and ITGA5:ITGB1. Binds to a site (site 2) which is distinct from the classical ligand-binding site (site 1) and induces integrin conformational changes and enhanced ligand binding to site 1. Induces cell proliferation in an integrin-dependent manner.
Synonyms: PLA2B; PLA2L; MOM1; PLA2; PLA2S; PLAS1; sPLA2
Tractability: Small molecule: a drug acting on it is in phase 2 or 3 trials; a structure with a bound ligand is known; a high-quality ligand is known; it has a high-quality binding pocket; it belongs to a druggable protein family. Antibody: UniProt places it where antibodies can reach, with high confidence; its Gene Ontology location is reachable by antibodies, with high confidence; UniProt predicts a signal peptide or a membrane-spanning region. PROTAC: ubiquitination databases record sites on it; its protein half-life has been measured; a small molecule that binds it is known.
Target class: Enzyme; Hydrolase
Gene: Protein-coding gene on chromosome 1 (19,975,431 to 19,980,462, reverse strand). Ensembl gene ENSG00000188257.
Subcellular location: Secreted; Cell membrane; Mitochondrion outer membrane
Pathways (Reactome):
Metabolism: Acyl chain remodelling of PC; Acyl chain remodelling of PE; Acyl chain remodelling of PG; Acyl chain remodelling of PI; Acyl chain remodelling of PS; Synthesis of PA
Immune System: Antimicrobial peptides
Gene Ontology:
Molecular function: phospholipase A2 activity; phospholipid binding; calcium ion binding
Biological process: angiotensin-activated signaling pathway; defense response to Gram-positive bacterium; low-density lipoprotein particle remodeling; phosphatidic acid metabolic process; phosphatidylcholine metabolic process; phosphatidylethanolamine metabolic process; phospholipid metabolic process; positive regulation of ERK1 and ERK2 cascade; regulation of neutrophil activation; intestinal stem cell homeostasis; negative regulation of T cell proliferation; phosphatidylglycerol metabolic process; positive regulation of cholesterol import; positive regulation of inflammatory response; positive regulation of macrophage derived foam cell differentiation; arachidonate secretion; lipid catabolic process
Cellular component: endoplasmic reticulum; extracellular exosome; extracellular region; mitochondrial outer membrane; plasma membrane; endoplasmic reticulum membrane; perinuclear region of cytoplasm
Genetic constraint (gnomAD): Loss-of-function variants: 5 observed, 9.06 expected, observed/expected ratio (o/e) 0.55, 90% interval 0.29 to 1.16. That is too few expected variants to judge how well the gene tolerates losing a copy. Missense variants: 129 observed, 174.78 expected, observed/expected ratio (o/e) 0.74, 90% interval 0.64 to 0.85. Synonymous variants: 68 observed, 67.04 expected, observed/expected ratio (o/e) 1.01, 90% interval 0.83 to 1.24.
Homologues: Orthologues: chimpanzee PLA2G2A (97% identical), macaque PLA2G2A (92% identical), rat Pla2g2a (72% identical), guinea pig Pla2g2a (68% identical), pig PLA2G2A (53% identical), tropical clawed frog pla2g2d (41% identical), mouse Pla2g2a (33% identical), Caenorhabditis elegans C03H5.4 (28% identical), Caenorhabditis elegans C07E3.9 (27% identical). Paralogues in human: PLA2G2E (50% identical), PLA2G2D (47% identical), PLA2G5 (43% identical), PLA2G2F (40% identical), PLA2G1B (38% identical), PLA2G10 (35% identical), PLA2G2C (33% identical), OC90 (30% identical).
Diseases named in the same sentence as PLA2G2A in open-access papers:
PLA2G2A is named in the same sentence as 142 diseases in open-access papers, as found by Europe PMC text mining. Sharing a sentence is not in itself a finding about the gene and the disease. The quoted sentences say what the papers report.
gastric cancer (19 papers, 2004 to 2025). A primary or metastatic malignant neoplasm involving the stomach. "Conversely, in gastric cancer, elevated expression of PLA2G2A is associated with improved patient survival." (PMID 39267107, 2024). "The increase in Helicobacter in Pla2g2a−/− mice can explain why mouse strains with a mutated Pla2g2a gene are more susceptible to intestinal tumorigenesis than those having an intact Pla2g2a gene and also accounts for an inverse correlation between PLA2G2A expression and gastric cancer in humans." (PMID 35448539, 2022). "In tumours, Pla2g2a has been identified as an independent predictor of survival that is modified by provision of a mixed oil containing fish oil in gastric cancer patients receiving chemotherapy." (PMID 41243421, 2025). "PLA2G2A has been identified as a tumor suppressor in gastric cancer, where it inhibits the invasion and migration of cancer cells." (PMID 39267107, 2024). "Previous studies have demonstrated that PLA2G2A functions as a tumor suppressor gene in esophageal squamous cell carcinoma and gastric cancer." (PMID 39267107, 2024). "In gastric cancer, patients with high PLA2G2A expression have a higher survival rate and a lower incidence of metastasis compared with patients with low expression." (PMID 36774376, 2023). "Patients with gastric cancer demonstrated significantly improved survival if the tumors had high PLA2G2A expression because the protein plays a crucial functional role in the suppression of metastasis genes." (PMID 38201587, 2023). "In contrast, high PLA2G2A expression suppresses gastric adenocarcinoma and gastric cancer progression." (PMID 38201587, 2023). "The PLA2G2A encodes phospholipase A2 group IIA which has been proposed as a TSG and a marker for metastasis and patient survival in gastric cancer." (PMID 16982006, 2006). "Furthermore, PLA2G2A and PLA2G4A have been implicated in the pathogenesis of various cancers, such as gastric cancer, colorectal cancer, and prostrate cancer." (PMID 37095470, 2023). "For example, in a meta-analysis of >300 tissue samples of gastric cancer, this hypothesis helped to identify a functional link between prognostic marker PLA2G2A and the EphB2 receptor." (PMID 22539975, 2012). "For example, in a recent meta-analysis of >300 tissue samples of gastric cancer, this hypothesis helped to identify a functional link between prognostic marker PLA2G2A and the EphB2 receptor." (PMID 20937113, 2010). "It will be of interest to determine whether the expression of PLA2G3 is related to the activation of the Wnt/β-cat/Tcf-4 pathway, as already suggested for PLA2G2A in gastric cancer." (PMID 18212756, 2008). "Beyond its potential diagnostic and prognostic significance, this result suggested that the activity of PLA2G2A may suppress progression or metastasis of human gastric cancer." (PMID 15610560, 2004). "Expression of ITGB5, TYMS, MYB, APOC1, CBX5, PLA2G2A, and KIF20A which is up-regulated in human gastric cancer tissues, was significantly decreased by vorinostat." (PMID 21931799, 2011). "Of these 12 genes, 7 genes highly expressed in gastric cancer tissues were down-regulated (ITGB5, TYMS, MYB, APOC1, CBX5, PLA2G2A, KIF20A) and 5 low-expressed genes were up-regulated after vorinostat treatment (SCGB2A1, TCN1, CFD, APLP1, NQO1." (PMID 21931799, 2011). "Using the top eight upregulated genes (SLPI, PLA2G2A, CXCL1, CCL20, REG1A, CLDN7, PI3, LGALS3) as a representative gene set for the high metabolic subcluster, we calculated the GSVA score of this gene set for each patient in the TCGA gastric cancer cohort." (PMID 38831933, 2024). "PLA2G2A, a new beta-catenin/TCF target gene, can inhibit gastric cancer migration and invasion." (PMID 35190739, 2022).
gastric cancer (continued). "Moreover, gene expression analysis of gastric cancer identified a collection of genes (ITGB5, TYMS, MYB, APOC1, CBX5, PLA2G2A, and KIF20A) whose expression was elevated in gastric tumor tissue and downregulated more than 2-fold by vorinostat treatment in gastric cancer cell lines." (PMID 21931799, 2011).
atherosclerosis (9 papers, 2011 to 2025). A disease characterized by the build-up of fatty material and calcium deposition in the arterial wall resulting in partial or complete occlusion of the arterial lumen. "The serum level of sPLA2-IIA also shows correlation with the risk of cardiovascular diseases, and Pla2g2a-Tg mice fed an atherogenic diet developed atherosclerosis." (PMID 21673902, 2011). "Additionally, PLA2G2A has been shown to be closely associated with fibrosis, and its elevated expression in other inflammatory diseases, such as ulcerative colitis and atherosclerosis, correlates with disease activity and tissue damage." (PMID 40160813, 2025). "With the focus of PLA2G2A studies being on its role in inflammation and atherosclerosis, studies on the actions of PLA2G2A in metabolism are quite limited." (PMID 34512555, 2021). "Additionally, experimental studies using atherosclerosis-prone mouse models demonstrated that genetic deletion of PLA2G2A significantly reduced plaque formation, highlighting its contribution to atherosclerotic development." (PMID 41472876, 2025). "Genes such as COMP (cartilage oligomeric matrix protein), CHI3L1, PLA2G2A, P2RY12, CR1, HPSE (heparanase), PTX3 and SERPINE1 were related to atherosclerosis." (PMID 34218797, 2021).
Obesity (9 papers, 2018 to 2023). Accumulation of substantial excess body fat. "Interestingly, all tissues of T2D patients showed altered expression of genes involved in the inflammation response—such as SOCS1 in WB; CCL20 and SLAMF1 in SAT; ACP5, FOS, and JUN in VAT; and PLA2G2A in LT, showing the relevance of the systemic chronic inflammation in obesity and T2D." (PMID 29466957, 2018). "Accordingly, PLA2G2A and PLA2G4A genes were up-regulated by omega-3 polyunsaturated fatty acids supplementation, whereas SLC27A2, CNR1, DAGLA, MGLL, FAAH, SLC27A1, and SLC27A2 genes were found to be down-regulated in people living with healthy obesity." (PMID 38024342, 2023).
psoriasis (9 papers, 2021 to 2025). An autoimmune condition characterized by red, well-delineated plaques with silvery scales that are usually on the extensor surfaces and scalp. "The highest increase of Il12rb2 (IL-23 receptor β chain) in Pla2g2a−/− mice relative to Pla2g2a+/+ mice might be a reflection of the increased Th17-type immunity, which could be associated with psoriasis in distal skin." (PMID 35076024, 2022). "In a model of psoriasis, the ectopic application of imiquimod elicited more severe ear edema, with a greater expression of several psoriasis markers, in Pla2g2a−/− mice than in Pla2g2a+/+ mice." (PMID 35448539, 2022). "PLA2G2A is often called ‘inflammatory secretory phospholipase A2′ (sPLA2) and is involved in many inflammatory pathologies such as rheumatoid arthritis and psoriasis." (PMID 35008966, 2022). "In fact, ear swelling and psoriasis marker expression in both genotypes at the UTokyo facility were similar to those in single-housed Pla2g2a–/– mice and cohoused Pla2g2a+/+ and Pla2g2a–/– mice at the TMIMS facility." (PMID 35076024, 2022). "Although bacteria species generating these unique lipids are currently unknown, the decrease in these anti-inflammatory bacterial lipids may account, at least in part, for the increased antitumor immunity and exacerbated psoriasis in Pla2g2a−/− mice." (PMID 35448539, 2022). "Furthermore, in the UTokyo animal facility, IMQ-induced psoriasis was comparable between Pla2g2a+/+ and Pla2g2a–/– mice." (PMID 35076024, 2022). "Genetic deletion of Pla2g2a in BALB/c mice ameliorates skin carcinogenesis and conversely exacerbates psoriasis, despite its negligible expression in the skin." (PMID 35076024, 2022). "Knockout of intestinal sPLA2-IIA in BALB/c mice leads to alterations in skin cancer, psoriasis, and anaphylaxis, while overexpression of sPLA2-IIA in Pla2g2a-null C57BL/6 mice induces systemic inflammation and exacerbates arthritis." (PMID 35448539, 2022). "The alteration in gut microbiota in Pla2g2a–/– BALB/c mice, as well as in PLA2G2A-transgenic C57BL/6 mice in which human sPLA2-IIA is overexpressed systemically, also impact the severity of arthritis and psoriasis." (PMID 35833146, 2022). "In support of this, Pla2g2a−/− mice housed in the Helicobacter-free animal facility did not display a psoriasis phenotype." (PMID 35448539, 2022). "In the present study using Pla2g2a–/– BALB/c mice, we provide evidence that sPLA2-IIA indeed contributes to shaping of the gut microbiota, thereby having secondary impacts on cancer and psoriasis in distal skin." (PMID 35076024, 2022).
colorectal cancer (7 papers, 2007 to 2024). A primary or metastatic malignant neoplasm that affects the colon or rectum. "Consistently, SELENOI was significantly upregulated in human colorectal cancer tissues, while PLA2G2A, PLA2G5, and ALOX15 were significantly downregulated." (PMID 38757622, 2024). "The importance of Pla2g2a in defense from intestinal bacteria was first identified in human colorectal cancers with high frequency of Pla2g2a gene deletion." (PMID 36050343, 2022). "PLA2G2A is part of the MAPK pathway, is upregulated in colorectal cancer, and is associated with poor clinical outcomes." (PMID 33287884, 2020). "Mice lacking expression of PLA2G2A have revealed increased colonic polyposis, and although gene mutations is not reported, lack of expression and sequence losses from this locus (chromosome band 1p36) are found in human colorectal carcinomas." (PMID 17201907, 2007). "Interestingly, the PLA2G2A, PLA2G2C, PLA2G2D, PLA2G2E, PLA2G2F and PLA2G5 genes reside within the same region of human chromosome 1 at p35–36.1, a region frequently altered in colorectal cancer." (PMID 18212756, 2008).
Alzheimer disease (6 papers, 2014 to 2024). A progressive, neurodegenerative disease characterized by loss of function and death of nerve cells in several areas of the brain leading to loss of cognitive function such as memory and language. "Pla2g2a is involved in mediating innate and adaptive immunity, and is upregulated in rat brain after cerebral ischemia and in human Alzheimer’s disease brain." (PMID 27926507, 2017). "mRNA and protein levels of cPLA2 IVA (PLA2G4A), sPLA2 IIA (PLA2G2A), COX-1 and -2 (PTGS1, PTGS2), mPGES1 (PTGES1), and LOX-12 and -15 (ALOX12B, ALOX15B), are increased in Alzheimer's disease in the frontal cortex, hippocampus, and cerebellum." (PMID 24963629, 2014).
Arthritis (6 papers, 2021 to 2023). Inflammation of a joint. "The PLA2G2A over-represented in synovial fluid samples of gouty arthritis patients was identified via liquid chromatography tandem mass spectrometry (LC–MS/MS), compared to Ankylosing Spondylitis (AS)." (PMID 34502281, 2021). "In further support of this conclusion, PLA2G2A-TG mice on the C57BL/6 strain also display an alteration in the gut microbiota, which leads to the exacerbation of systemic inflammation and arthritis." (PMID 37189415, 2023).
breast carcinoma (6 papers, 2017 to 2024). "A type of PLA2G2A + cancer-associated fibroblasts that was enriched in HER2+ breast cancer and showed high expression levels of genes that can interact with immune cells." (PMID 39726782, 2024). "Additionally, we identify a subtype of PLA2G2A+ cancer-associated fibroblasts enriched in HER2+ breast cancer patients that promotes immune infiltration." (PMID 36357424, 2022). "In this study, we found a type of PLA2G2A+ CAFs that was enriched in HER2+ breast cancer and showed high expression levels of genes that can interact with immune cells." (PMID 36357424, 2022). "Immunohistochemical (IHC) staining in human breast cancer tissues further revealed that PLA2G2A+ CAFs were more abundant in HER2+ tumors than in luminal tumors." (PMID 36357424, 2022). "In short, we identified 3 CAF subsets in breast cancer patients and demonstrated enrichment of PLA2G2A+ CAFs in HER2+ tumors, and these may be the main microenvironmental factors that determine the immune infiltration in breast cancer." (PMID 36357424, 2022). "Moreover, we identify a type of cancer-associated fibroblast (CAF) expressing PLA2G2A that can interact with immune cells and that is enriched in HER2+ breast cancer." (PMID 36357424, 2022). "PLA2G2A was also positively correlated with the CD45 antigen PTPRC, B-cell marker CD79A, and CD8 T cell marker CD8A in breast cancer patients." (PMID 36357424, 2022). "Another interesting observation is that PLA2G2A+ CAFs were present in both the PT and the LNMT of HER2+ patients; however, they were not present in the LNMT of patients with luminal breast cancer." (PMID 36357424, 2022).
Sepsis (6 papers, 2013 to 2023). Sepsis is defined as life-threatening organ dysfunction caused by a dysregulated host response to infection. "PLA2G2A is a potent mediator of the inflammatory process and also proatherogenic, implicated in various clinical conditions, including sepsis." (PMID 36589459, 2022). "SNPs in the genes for TLR2 (rs3804099), TLR5 (rs5744105), IL-10 (rs1800896), and PLA2G2A (rs1891320) were associated with sepsis." (PMID 24310803, 2013). "The authors concluded that the allelic variants PLA2G2A, TLR2, TLR5 and IL-10 could influence the risk of sepsis among preterm infants." (PMID 24310803, 2013).